RNU6-280P (RNA, U6 small nuclear 280, pseudogene)
Synonyms: RNU6-1221P
Gene: Small nuclear RNA gene on chromosome 6 (67,546,651 to 67,546,754, forward strand). Ensembl gene ENSG00000201015.
Homologues: Orthologues: chimpanzee U6 (99% identical), macaque U6 (94% identical), mouse Gm22450 (89% identical), rabbit U6 (89% identical), rat U6 (88% identical), pig U6 (86% identical), rat U6 (86% identical), guinea pig U6 (80% identical). Paralogues in human: RNU6-211P (90% identical), RNU6-1145P (89% identical), RNU6-1316P (88% identical), RNU6-15P (88% identical), RNU6-20P (88% identical), RNU6-1152P (88% identical), RNU6-166P (88% identical), RNU6-25P (88% identical), RNU6-310P (88% identical), RNU6-35P (88% identical), RNU6-38P (88% identical), RNU6-393P (88% identical), and 1288 more.